HERC2 (HECT and RLD domain containing E3 ubiquitin protein ligase 2)
Diseases named in the same sentence as HERC2 in open-access papers (continued):
Sharing a sentence is not in itself a finding about the gene and the disease.
osteosarcoma (3 papers, 2019 to 2021). A usually aggressive malignant bone-forming mesenchymal neoplasm, predominantly affecting adolescents and young adults. "In osteosarcoma, the increase of HERC2-binding protein SOX18 enhances cell proliferation correlating with a decrease in HERCs mRNA levels, especially those of HERC2." (PMID 31447701, 2019). "The expression of HERC2 and SOX18 in osteosarcoma is significantly negatively correlated and SOX18 has been tested to play a significant part in the proliferation, migration, invasion and apoptosis of osteosarcoma cells." (PMID 34820159, 2021). "Besides, HERC2 interacts with SOX18, which is overexpressed in osteosarcoma cells." (PMID 34820159, 2021).
ovarian cancer (3 papers, 2021 to 2024). A primary or metastatic malignant neoplasm involving the ovary. "HERC2 also contains a non‐heme‐binding cyt‐b5 like domain (cyt‐b5, residues V1207–L1283), a Mind‐bomb‐HERC2 domain (M‐H, residues S1859–P1932), and a downregulated in ovarian cancer domain (DOC, residues Q2774–R2914), whose roles and functions remain unclear." (PMID 39565083, 2024).
Crohn disease (2 papers, 2013 to 2017). A gastrointestinal disorder characterized by chronic inflammation involving all layers of the intestinal wall, noncaseating granulomas affecting the intestinal wall and regional lymph nodes, and transmural fibrosis. "HERC2 has been genetically associated with Crohn's disease, sarcoidosis and its acute and chronic subphenotypes." (PMID 29228712, 2017). "This SNP is located in the HERC2 gene known to be involved in iris colour and to show population stratification in Europe, but the HERC2 gene has also been reported to be associated with Crohn’s disease in a Dutch-Belgian cohort study." (PMID 24147066, 2013).
diabetes (2 papers, 2021). "Further studies have shown that lncRNA-Fendrr promotes NLRC4-mediated pyroptosis in microglia model of diabetes-cerebral I/R, but HERC2 reversed the effect of lncRNA-Fendrr." (PMID 33858325, 2021).
freckles (2 papers, 2025). Disorders of increased melanin pigmentation that develop without preceding inflammatory disease. "The significant associations observed in our study suggest that SNPs of rs1129038 of the HERC2 gene may influence the expression of other pigment-related genes, thereby contributing to the risk of melasma development." (PMID 39940926, 2025). "Significant associations were observed for the TYR gene (rs1042602), HERC2 gene (rs1129038), and SLC24A5 gene (rs1426654) polymorphisms, highlighting their potential roles in melasma susceptibility." (PMID 39940926, 2025). "Polymorphisms rs1129038 of the HERC2 gene and rs1426654 (A > G) of the SLC24A5 gene also showed significant associations with melasma, particularly for the CC and GG genotypes, respectively, suggesting their involvement in melasma risk." (PMID 39940926, 2025). "This study investigates the association between genetic variants in SLC45A2, TYR, HERC2, and SLC24A5 genes and the severity of melasma in women of reproductive age." (PMID 39940926, 2025). "Thus, this study presents a novel investigation into the association of genetic polymorphisms in SLC45A2, TYR, HERC2, and SLC24A5 in African women with melasma, a population that has been under-represented in genetic research on pigmentation disorders." (PMID 39940926, 2025). "By examining polymorphisms in SLC45A2, TYR, HERC2, and SLC24A5, this pilot study highlights the potential genetic factors that may influence melasma susceptibility and severity in a population with distinct pigmentation characteristics." (PMID 39940926, 2025). "However, despite these limitations, this pilot novel study demonstrates valuable insights into melasma development in women of African descent by exploring the genetic role of specific SNPs (SLC45A2, TYR, HERC2, and SLC24A5) in this under-represented population." (PMID 39940926, 2025).
hepatocellular carcinoma (2 papers, 2023). A malignant tumor that arises from hepatocytes. "Among these inflammatory diseases there are some related to the digestive system and, recently, HERC2 has also been described to promote inflammation-driven cancer stemness and immune evasion in hepatocellular carcinoma (HERC2 section)." (PMID 36902336, 2023).
oculocutaneous albinism (2 papers, 2019 to 2023). Oculocutaneous albinism (OCA) describes a group of inherited disorders of melanin biosynthesis characterized by a generalized reduction in pigmentation of hair, skin and eyes and variable ocular findings including nystagmus, reduced visual acuity and photophobia. "The human HERC2 gene locus is upstream of that of the OCA2 gene (mutated in oculocutaneous albinism) and certain HERC2 SNPs can interfere OCA2’s expression thus affecting eye, skin, and hair pigmentation." (PMID 31447701, 2019).
Parkinson disease (2 papers, 2016 to 2023). A progressive degenerative disorder of the central nervous system characterized by loss of dopamine producing neurons in the substantia nigra and the presence of Lewy bodies in the substantia nigra and locus coeruleus. "A recent study also suggests the involvement of HERC2 in Parkinson's disease, it would be interesting to analyze in future studies the HERC2 role in the midbrain dopaminergic neurons of Herc2+/530 mice." (PMID 27528230, 2016). "In addition, due to the association between HERC2 and LRRK2 proteins, it has been suggested that HERC2 might be involved in Parkinson’s disease pathogenesis." (PMID 36902336, 2023).
schizophrenia (2 papers, 2021 to 2022). A major psychotic disorder characterized by abnormalities in the perception or expression of reality. "These analyses identified overlapping CNVs in lncRNAs of the ASD-related genes, HERC2, and GOLGA8, in the 15q11.1—11.2 schizophrenia/ASD-associated duplication region, suggesting that the pathogenesis of SELENBP1 upregulation in schizophrenia may be related to that of ASD." (PMID 36512497, 2022). "We applied the framework to seventeen phenotypes and found well-replicated genes such as HERC2 and OCA2 for hair and eye color, and novel genes such as ZNF773 and PCNT for schizophrenia." (PMID 34535759, 2021).
T-cell prolymphocytic leukemia (2 papers, 2019 to 2022). A slow-growing type of leukemia (blood cancer) in which too many lymphocytes are found in the bone marrow and/or blood. "Recurrent mutations of both HERC1 and HERC2 have also been detected in T cell prolymphocytic leukemia with a frequency of approximately 10%." (PMID 35054018, 2022).
acute liver failure (1 paper, 2024). Rapid deterioration of liver function causing encephalopathy and coagulopathy. "We first investigated the expression of HERC2 in human liver explant samples from patients transplanted for APAP‐induced acute liver failure with an opened snRNA‐seq database (GSE223581)." (PMID 39440550, 2024).
age-related macular degeneration (1 paper, 2025). Age-related loss of vision in the central portion of the retina (macula), secondary to retinal degeneration. "A deep learning model trained to predict age-related macular degeneration (AMD) found that patients with the minor allele at the rs12913832/HERC2 locus, associated with retinal pigmentation in our study, were more likely to have false positives for age-related macular degeneration." (PMID 39746957, 2025).
Astigmatism (1 paper, 2018). A type of refraction error associated with abnormal curvatures on the anterior and/or posterior surface of the cornea. "Three of these loci also demonstrated genome-wide significant association with refractive astigmatism: LINC00340, HERC2/OCA2 and NPLOC4/TSPAN10." (PMID 30306274, 2018). "With the exception of the association signal at HERC2/OCA2, the majority of the astigmatism susceptibility loci have demonstrated association with spherical equivalent-related traits in previous GWAS analyses." (PMID 30306274, 2018). "For refractive astigmatism, markers achieving genome-wide significant association clustered in three regions: LINC00340, (top marker: rs12196123, P = 1.60 × 10−15), HERC2 (top marker: rs1129038, P = 2.30 × 10−11) and TSPAN10/NPLOC4 (top marker: rs34635363, P = 2.00 × 10−9)." (PMID 30306274, 2018). "The identification of 3 genes (HERC2, OCA2 and TSPAN10) associated with eye colour and astigmatism implies that certain eye colour(s) may confer susceptibility to astigmatism or that these eye colour-related genes have distinct, pleiotropic actions that lead to astigmatism." (PMID 30306274, 2018).
B-cell lymphoma (1 paper, 2010). "These two CNVs overlap the genes hect domain and RLD 2 (HERC2) associated with skin, hair and eye pigmentation (OMIM: 227220), and BCL8 B-cell CLL/lymphoma 8 (BCL8) which has been implicated potentially in B-cell lymphoma (OMIM: 601889)." (PMID 20500880, 2010).
brain cancer (1 paper, 2022). A primary or metastatic malignant neoplasm affecting the brain. "Additionally, TTI2 in prostate, APC in breast, MAD2L2 in pan-cancer, HERC2 in prostate, and MDN1 in brain cancer associated with the mutation component dMMRICA." (PMID 35764656, 2022).
Christianson syndrome (1 paper, 2021). A very rare form of syndromic intellectual deficit characterized by microcephaly, severe developmental delay or regression, hypotonia, abnormal movements, and early-onset seizures.
Chronic Myeloid Leukemia (1 paper, 2022). "Indeed, though both genes appear to be severely downregulated in chronic myeloid leukemia cells, the effect of Dasatinib on the HERC1 and HERC2 gene expression is different." (PMID 35054018, 2022).
Cirrhosis (1 paper, 2023). A chronic disorder of the liver in which liver tissue becomes scarred and is partially replaced by regenerative nodules and fibrotic tissue resulting in loss of liver function. "In addition, Cox regression analysis suggested that HERC2 expression was identified as an independent prognostic factor for HCC patients with cirrhosis, and high HERC2 expression led to a poor prognosis." (PMID 36721234, 2023).
colon cancer (1 paper, 2022).
Corneal astigmatism (1 paper, 2018). "Single marker-based association tests for corneal astigmatism identified four genome-wide significant loci (P < 5 × 10−8) near the genes ZC3H11B (1q41), LINC00340 (6p22.3), HERC2/OCA2 (15q13.1) and NPLOC4/TSPAN10 (17q25.3)." (PMID 30306274, 2018).
encephalopathies (1 paper, 2025). "The genes NDN, SNRPN, and UBE3A are known for their association with Prader–Willi syndrome; GABRB and GABRA5 are associated with encephalopathies; OCA2 and HERC2 are linked to skin pigmentation." (PMID 40149731, 2025).
gastric carcinoma (1 paper, 2021). A carcinoma that arises from epithelial cells of the stomach. "Similarly diverse roles of USP33 in deubiquitinating Parkin gene, HERC2, centrosome biogenesis, tumor progression of gastric carcinoma as well as DENV neuropathogenesis are well established." (PMID 33936086, 2021).
Hypertension (1 paper, 2021). The presence of chronic increased pressure in the systemic arterial system. "Overexpression of SIRT1 in murine endothelial cells prevented hypertension and adverse arterial remodeling; however, a knockdown of HERC2 abolished any beneficial effects of SIRT1, suggesting a neuroprotective regulatory role of HERC2." (PMID 34252155, 2021).
inflammatory bowel disease (1 paper, 2017). A spectrum of small and large bowel inflammatory diseases of unknown etiology. "Comparative genetic analysis of inflammatory bowel disease and type 1 diabetes implicates HERC2 loci." (PMID 29228712, 2017).
keratinocyte carcinoma (1 paper, 2024). A skin cancer arising from the keratin-producing cells of the epidermis. "The variant rs12916300, located within HERC2, has been reported to be associated with the development of keratinocyte cancer and squamous cell carcinoma, with allele-T identified as the risk allele." (PMID 40040643, 2024).
lactose intolerance (1 paper, 2017). "Other relevant SNPs carry the ancestral allele, including HERC2 and LCT, which suggest dark-coloured eyes and lactose intolerance." (PMID 28556824, 2017).
liver failure (1 paper, 2024). A liver disease characterized by the liver losing or has lost all of its function. "We observed a significant upregulation of HERC2 expression in the specific hepatocyte clusters expanded in APAP‐induced liver failure." (PMID 39440550, 2024).
lung carcinoma (1 paper, 2023). "Consistent with this idea, RNF8 localizes to the cytoplasm where it interacts with HERC2 and NEURL4 in neurons, IKKα/β, as well as Akt in lung cancer." (PMID 37468549, 2023).
lung disease (1 paper, 2025). "The remaining 11 genes in the region encode proteins associated with neurologic disorders (APBA2, CHRFAM7A, MTMR10, FAN1), skin and eye pigmentation or development (OCA2, HERC2, TJP1, TRPM1), nephritis (ARHGAP11B, MTMR10, FAN1), and lung disease (ENTREP2, NSMCE3)." (PMID 40013929, 2025).
lupus (1 paper, 2017). "In addition, in a mouse model that simulates lupus progression, animals experienced an increased expression of MAP17 connected with a decrease in RFX3, a negative regulator of HLAs, and decreases in HERC2 and ADNP." (PMID 29228712, 2017).
non-small cell lung carcinoma (1 paper, 2016). A group of at least three distinct histological types of lung cancer, including non-small cell squamous cell carcinoma, adenocarcinoma, and large cell carcinoma. "We retrospectively analyzed 71 paraffin-embedded tumor samples from advanced non-small-cell lung cancer patients treated with first-line platinum based chemotherapy and measured the mRNA expression levels of BRCA1, RNF8, UBC13 and HERC2 using real-time PCR." (PMID 27179511, 2016).
Obesity (1 paper, 2015). Accumulation of substantial excess body fat. "While we cannot exclude that the HERC2 variant may contribute to the neurological presentation of our cases, it is unlikely that it accounts for the obesity." (PMID 26029708, 2015). "Similarly, no obesity has been reported in HERC2-mutated patients." (PMID 26029708, 2015).
oculocutaneous albinism type 2 (1 paper, 2018). Oculocutaneous albinism type 2 (OCA2) is a type of OCA and the most common form of OCA seen in the African population, characterized by variable hypopigmentation of the skin and hair, numerous characteristic ocular changes and misrouting of the optic nerves at the chiasm. "The protein coding gene HERC2 (HECT and RLD domain containing E3 ubiquitin protein ligase 2) and its neighbouring gene OCA2 (Oculocutaneous albinism type 2) on chromosome 15 (15q13.1) have both previously demonstrated association with eye, skin and hair pigmentation." (PMID 30306274, 2018).
renal carcinoma (1 paper, 2022). A carcinoma arising from the epithelium of the renal parenchyma or the renal pelvis. "In renal cancer, higher HERC2 gene expression correlates with better patient prognosis, supporting the hypothesis that HERC2 may act as a tumour suppressor." (PMID 36241744, 2022).
thyroid cancer (1 paper, 2023). "Moreover, SNPs associated with thyroid cancer in three thyroid cancer driver genes (CUX1, HERC2 and RGPD3) were under positive selection in East Asian and European populations, consistent with the high incidence of thyroid cancer in these populations." (PMID 37098512, 2023). "Interestingly, SNPs associated with thyroid cancer (THCA) in three THCA driver genes were found to be under positive selection in the East Asian population (CUX1 and RGPD3) and the European population (HERC2)." (PMID 37098512, 2023).
uterine cancer (1 paper, 2023). Primary or metastatic malignant neoplasm involving the uterine corpus and/or the cervix. "Same information for predictive models of (b) IDH1-d, (c) SMARCA4-d, (d) CDKN2A-d, (e) HERC2-d, and (f) PTEN-d in central nervous system (CNS) cancers and (g) uterine cancers." (PMID 36883553, 2023).
vitiligo (1 paper, 2023). Generalized well circumscribed patches of leukoderma that are generally distributed over symmetric body locations and is due to autoimmune destruction of melanocytes. "Previous studies have shown that an elevated risk of vitiligo is associated with HERC2 variations, which have a significant impact on determining skin and iris color besides the OCA2." (PMID 37239478, 2023).